INS (insulin)
Diseases named in the same sentence as INS in open-access papers (continued):
Sharing a sentence is not in itself a finding about the gene and the disease.
diabetes (continued). "Although participants generally spoke positively about advances in diabetes technologies (including insulin pumps, artificial pancreas, and looping systems), some also expressed concern regarding information overload from the abundance of CGM data." (PMID 39509700, 2024). "Curcumin exerts its effects through NF-κB pathway inhibition, activation of the Nrf2 pathway, and modulation of insulin signalling, thereby offering therapeutic benefits in diabetes, obesity, and cardiovascular diseases." (PMID 39204080, 2024). "This case emphasizes the importance of a routine physical examination, particularly abdominal inspection, when evaluating patients with diabetes on insulin as well as patient education on proper insulin administration and rotation of sites." (PMID 39372830, 2024). "Conversely, heart failure can also contribute to the onset of diabetes by disrupting the body’s metabolic processes and amplifying insulin resistance." (PMID 38298910, 2024). "Insulin-sensitive obese subjects had a 40% lower incidence of diabetes than insulin-resistant obese subjects." (PMID 38710948, 2024). "Diabetes mellitus is a common metabolic disorder characterized by impairments in insulin secretion or action." (PMID 39684343, 2024). "This comparison helps to highlight the range of options available to diabetes patients, from basic glucose monitors to sophisticated automated insulin delivery systems." (PMID 39064398, 2024). "PTP1B is the most important phosphatase in the insulin signaling cascade and directly phosphorylates insulin receptors (IR and IRS 1) to inhibit them, altering insulin production and increasing blood glucose levels during diabetes." (PMID 38924022, 2024). "Type 1 diabetes mellitus (T1DM) is a chronic condition primarily managed with insulin replacement, leading to significant treatment costs." (PMID 39451804, 2024). "A key step in perioperative diabetes control is that of managing medications, including oral and injectable non-insulin antihyperglycemics and insulin." (PMID 39199594, 2024). "The GSH/GSSG ratio in the plasma affects cellular responsiveness to glucose, and an increase in this ratio improves the action of peripheral insulin, reduces the extent of oxidative damage, and increases insulin sensitivity in patients with diabetes." (PMID 39170342, 2024). "GHRH is involved in the regulation of insulin secretion from the pancreas and abnormal GHRH signaling can impair insulin secretion, leading to hyperglycemia and contributing to the development or worsening of diabetes." (PMID 39560873, 2024). "Insulin therapy remains a cornerstone in Type 2 Diabetes Mellitus (T2DM) management, prescribed to millions worldwide." (PMID 39001440, 2024). "It is beneficial against diabetes through mechanisms such as improving insulin sensitivity, promoting glucose uptake, and lowering blood sugar levels." (PMID 38543024, 2024). "Type 1 diabetes mellitus (T1DM) is a chronic disease with significant treatment costs primarily attributed to the requirement for insulin replacement." (PMID 39451804, 2024). "In diabetes, the limbal cell migration is increased, potentially leading to the inflammatory state delaying wound healing, but is restored upon systemic insulin administration." (PMID 38534414, 2024). "Health conditions that were present for 10% to 15% of participants were depression, diabetes (controlled by insulin or equivalent), chronic bad chest, and cerebrovascular disease." (PMID 38182985, 2024). "Although insulin’s vital role in both types of diabetes, it is considered one of the harmful medications if used incorrectly." (PMID 38594659, 2024). "Subgroup analyses were conducted in terms of sex, age, duration of diabetes, insulin therapy, and oral pharmacotherapy." (PMID 38469168, 2024).
diabetes (continued). "Pathogenesis of hyperfiltration in diabetes is complex, comprising numerous mechanisms and mediators, with a prominent role for hyperglycemia, distorted insulin levels, and proteinuria, especially in early diabetes and prediabetes." (PMID 39258389, 2024). "Most cases of diabetes can be classified into two types: Type 1 diabetes (T1D) is most common in children and results from the destruction of insulin-producing beta cells, mostly by autoimmune mechanisms." (PMID 38470940, 2024). "Basal insulin continues to be a vital part of therapy for many people with diabetes.First attempts to prolong the duration of insulin formulations were through thedevelopment of suspensions that required homogenization prior to injection." (PMID 38224978, 2024). "Women with GDM had a significantly more stable GP, fewer HE, and lower insulin requirements than those with pre-existing diabetes." (PMID 40071056, 2024). "Diabetes is a chronic disease which occurs due to the insufficient production of insulin by the pancreas or due to the inability of the body to use insulin effectively." (PMID 39078862, 2024). "This difference was driven by the group who required insulin at baseline (n = 5), of which four (80.0%) were admitted to a high-dependency unit with diabetes-related complications, and three (60.0%) required omission of at least one cycle of chemotherapy." (PMID 38392055, 2024). "Nocturnal hypoglycemia is a major concern for most individuals living with diabetes who are on insulin therapy." (PMID 38510652, 2024). "Patients with T2DM and DR were more likely to use insulin (OR=3.63, 95% CI 1.89-7.00), have a longer duration of diabetes (OR=1.04 per year, 95% CI 1.02-1.07), and exhibit higher systolic blood pressure (OR=1.01 per mmHg, 95% CI 1.00-1.02)." (PMID 39872596, 2024). "As a chronic disease, diabetes occurs either when the body cannot produce enough insulin or cannot effectively use the insulin." (PMID 39835306, 2024). "Diabetes is one of the four major types of NCDs and it occurs when the body does not produce enough insulin or cannot effectively use the produced insulin." (PMID 38999923, 2024). "C. sativus can increase the level of insulin secretion from pancreatic beta cells and can be considered in the treatment of diabetes in the future." (PMID 38419885, 2024). "An increasing number of evidence suggests that unresolved or dysregulated ER stress signaling pathways play a pivotal role in β-cell failure leading to insulin secretion defect and diabetes." (PMID 38966213, 2024). "This review aims to update our knowledge related to diabetes mellitus by gathering the most authoritative studies on zebrafish as a chemical, dietary and insulin induction, and genetic model for diabetes research." (PMID 38279951, 2024). "Another substantial improvement in diabetes treatment in the last decades includes the development of continuous subcutaneous (SC) insulin infusion pumps (insulin pumps) and sensors for SC continuous glucose monitoring (CGM)." (PMID 37715091, 2024). "Insulin and C-peptide levels were decreased, and the glucose-induced suppression of glucagon was impaired in both diabetes groups (all p < 0.0001 versus." (PMID 39596226, 2024). "Modern medical research indicates that mulberry twigs can alleviate diabetes, reduce cholesterol and blood sugar levels, enhance insulin sensitivity, and prevent liver damage, among other beneficial effects." (PMID 39274829, 2024). "Patients with diabetes are divided into type I diabetes and type II diabetes according to different states of insulin secretion insufficiency or insulin resistance." (PMID 38645437, 2024). "The Bigfoot Unity diabetes management system integrates a smart pen cap with the Freestyle Libre 3 to transmit insulin dosing information between the pen and mobile app." (PMID 39091290, 2024).
diabetes (continued). "Insulin resistance can also lead to an increase in blood sugar, and the body secretes more insulin to maintain normal blood sugar levels, leading to hyperpancreatic islet emia and the eventual development of diabetes mellitus type 2." (PMID 39055491, 2024). "Oral insulin (INS) is predicted to have the most therapeutic advantages in treating diabetes to repress hepatic glucose production through its potential to mimic the endogenous insulin pathway." (PMID 38214820, 2024). "Significant differences were observed for age, smoking status, body mass index, waist circumference, fat percentage, glucose, insulin, C-reactive protein, diabetes prevalence, lipid profiles, arterial stiffness, and blood pressure levels." (PMID 38218806, 2024). "The United Kingdom Prospective Diabetes Study (UKPDS) was the first study in which intensive blood glucose control with either insulin, sulphonylurea, or metformin, was assessed versus diet control in patients with T2DM." (PMID 39911238, 2024). "More than 60% of the origin of fat accumulation in the liver is thought to be an influx of free fatty acids due to lipolysis of adipocytes, which are increased in diabetes due to impaired insulin action in adipocytes." (PMID 39513056, 2024). "In the early stages of type 2 diabetes mellitus, the body compensates for decreased insulin sensitivity by increasing insulin secretion." (PMID 38611884, 2024). "Pathway enrichment analyses of the combined upregulated and downregulated genes revealed pathways involved in translation initiation, nonsense-mediated decay, insulin secretion, and maturity-onset of diabetes of the young (MODY)." (PMID 38409327, 2024). "By providing insights into glucose trends and patterns, CGM facilitates timely insulin therapy and dietary intake adjustments, empowering patients to manage their diabetes more effectively." (PMID 39246894, 2024). "Patients taking oral medications were 55% less likely to practice good diabetes self-care practices than those taking insulin injections, as per a study conducted in Iran, Addis Ababa and Bahirdar." (PMID 39280819, 2024). "After diabetes onset, C-peptide declines; however, it persists detectably for more than 20 years despite the use of insulin." (PMID 38792571, 2024). "Interviews explored multifaceted dimensions (e.g., usability) on two EML applications for the 2021 WHO EML–long-acting insulin analogues for diabetes and immune checkpoint inhibitors for lung cancer." (PMID 38206901, 2024). "Knowledge of the insulin structure is essential for producing recombinant insulin for diabetes treatment and for designing insulin analogs with improved properties." (PMID 39408998, 2024). "Hypoglycemia is an extremely common side effect of insulin therapy experienced mainly by patients with type 1 diabetes mellitus (T1DM)." (PMID 39487352, 2024). "Repeated exposures to insulin-induced hypoglycaemia in people with diabetes progressively impairs the counterregulatory response (CRR) that restores normoglycaemia." (PMID 38017352, 2024). "Initially, pancreatic beta cells secrete more insulin to preserve glucose homeostasis; however, with time, insulin production decreases, leading to diabetes." (PMID 39272654, 2024). "PTMs mediates the development of diabetes mellitus by affecting insulin homeostasis, glucose metabolism, diabetic complications, gluconeogenesis, and β‐cell function." (PMID 39355507, 2024). "Alternatively, some studies have proposed that IF can help with diabetes since it improves insulin sensitivity." (PMID 38847940, 2024). "Alcohol intake leads to changes in insulin secretion by pancreatic β-cells and can also mediate insulin resistance, resulting in impaired glucose metabolism that can lead to diabetes." (PMID 38221613, 2024).
diabetes (continued). "At the time of joining the one-year intervention, the median duration (interquartile range) of diabetes was 4.3 (1.3–8.8) years and most participants (84.3%) were on glucose-lowering medication [including oral hypoglycemic agents (OHAs) or insulin or both]." (PMID 38701059, 2024). "Type 2 diabetes mellitus (T2DM), affecting 95% of people, is caused by increased blood glucose levels due to insufficient pancreatic insulin secretion or insulin resistance in body cells." (PMID 39458809, 2024). "Diabetes mellitus (DM), a group of metabolic disorders, is characterized by hyperglycemia, resulting from defects in insulin action, insulin secretion, or a combination of both." (PMID 39224109, 2024). "Diabetes mellitus (DM) is a chronic metabolic disorder characterised by high blood sugar (BS) levels due to impaired insulin production or insulin resistance." (PMID 38881209, 2024). "It is worth mentioning that one study specifically incorporated all adult diabetes patients who were actively receiving insulin therapy." (PMID 39553423, 2024). "In patients with diabetes, advanced age, diabetes duration, obesity, presence of coronary artery disease (CAD), insulin use, CV risk factors such as hypertension and hypercholesterolemia are all independent risk factors for the development of HF." (PMID 39342254, 2024). "Our findings shed light on insulin secretion control, providing potential avenues for therapeutics against diabetes." (PMID 38731926, 2024). "The βIRKO mice have worsening glucose tolerance over time despite the absence of insulin resistance in peripheral tissues, suggesting that impaired insulin action in β cells is involved in the development of type 2 diabetes mellitus." (PMID 39513056, 2024). "Transplanted human α-cells reverse diabetes in mice and sustain insulin production for at least six months, retaining their original cell identity markers." (PMID 39057094, 2024). "The audit, conducted on the clinical notes of 85 patients with diabetes, showed that one in four patients on insulin is affected by a prescription error within 48 h of hospital admission." (PMID 39457586, 2024). "Diabetes is a complex metabolic disorder characterized by elevated blood glucose levels, resulting from a disruption in insulin secretion, reduced insulin sensitivity, or a combination of both mechanisms." (PMID 38681576, 2024). "For this purpose, the expression of RBP4 has been studied in five experimental groups of mice: controls, diabetics, insulin-treated diabetics, mice that overexpress PTHrP at the renal level, and a group of diabetics." (PMID 39795999, 2024). "In type 1 diabetes mellitus (T1DM), FABP4 plays a regulatory role in glucose and lipid metabolism, particularly in ketogenesis during the insulin-deficient state." (PMID 38731797, 2024). "Diabetes mellitus, characterized by abnormal insulin secretion, impaired insulin action, or both, is a chronic metabolic disease that results from the interaction of genetic and environmental factors." (PMID 39170740, 2024). "Aggravating high-fat-diet-induced pre-diabetes symptoms.Female mice exhibit weight gain, elevated serum insulin levels, impaired glucose tolerance.Male mice show only impaired glucose tolerance." (PMID 38251002, 2024). "Insulin therapy has been the earliest treatment for pancreatogenic diabetes since T3cDM was initially categorized as a specific subtype of DM." (PMID 38792534, 2024). "Most Parikweneh participants named insulin as a biomedical remedy for diabetes (62.5%; 30/48), whereas only some named at least one antidiabetic pill, i.e. metformin, stagid, amaryl, velmetia or glibenclamide (8.33%; 4/48)." (PMID 39237925, 2024). "When IR was coupled with dysfunction of pancreatic β-cells, the cells responsible for insulin secretion, it led to the onset and progression of diabetes." (PMID 39737158, 2024).
diabetes (continued). "The introduction of biosimilar insulins in the Indian healthcare market is the key to making insulin accessible to every patient with diabetes." (PMID 38910730, 2024). "In Boston, Dr. Elliot P. Joslin (the first American diabetes doctor) treated Marie with insulin, and the couple decided to contact Professor Macleod to request permission to manufacture and sell insulin in Scandinavia." (PMID 38540146, 2024). "Diabetes mellitus is an endocrine disorder characterized by chronic hyperglycemia resulting from defects in insulin secretion or action or both." (PMID 39444449, 2024). "In mice with obesity or a high-fat diet, deletion of XBP1 in β-cells results in diabetes mellitus and exacerbates glucose intolerance by impairing insulin secretion." (PMID 38509524, 2024). "Patients with T2DM were treated in line with national guidelines for diabetes management at that time, majority with SGLT2i, metformin, and/or insulin." (PMID 38902687, 2024). "Insulin and glucagon levels were lower in the type 1 diabetes group compared with the type 2 diabetes group, and similar to those in the non-diabetes group." (PMID 39078488, 2024). "Almond has a high fiber content, which helps in ameliorating diabetes by suppressing appetite and lowers blood sugar levels via increasing insulin production and decreasing the stomach’s emptying time." (PMID 39519546, 2024). "Diabetes is driven by decreased response to insulin (insulin resistance) or insufficient insulin production and diagnosed by hyperglycemia." (PMID 38922352, 2024). "Gastrodin has also been reported to increase the activity of pancreatic β-cells and stimulate insulin secretion, ultimately improving diabetes." (PMID 38322269, 2024). "The generation of reactive oxygen species leads to a reduction in anti-oxidant enzyme production, which promotes disruption of insulin-secreting beta cells thereby, resulting in a rise in blood sugar levels as an incidence of diabetes." (PMID 38664520, 2024). "For diabetes management, MNs enable continuous glucose monitoring, diabetic wound healing, and painless insulin delivery." (PMID 39458672, 2024). "Additional etiologies of diabetes include dysfunction in insulin-sensing hepatic, muscle, and adipose tissues as well as immune cells." (PMID 38404962, 2024). "T1DM is an autoimmune disease that targets pancreatic cells and drastically reduces insulin secretion, leading to elevated blood glucose levels, accounting for approximately 10% of diabetes cases." (PMID 39682954, 2024). "The eight patients with de novo diabetes‐related ketoacidosis received treatment with insulin, of which three also received immunosuppressive therapy." (PMID 38899457, 2024). "Studies indicated that the FII can predict postprandial insulin response more accurately than CC, and that a high DII and DIL diet is associated with the development of metabolic syndrome, insulin resistance, and diabetes." (PMID 38474713, 2024). "One study suggests that arachidonic acid improves insulin sensitivity and prevents the onset of diabetes in rats fed a high-fat diet." (PMID 38279237, 2024). "Her insulin treatment (including accessories such as insulin syringes, glucose meter, and test strips) was provided free of charge through the Changing Diabetes in Children (CDiC) program in Cameroon." (PMID 39420387, 2024). "The data on missed insulin doses highlight the challenge of adherence in pediatric diabetes, a well-documented issue that can significantly impact disease control and management outcomes." (PMID 38590482, 2024). "Diabetes mellitus is a chronic metabolic disease characterized by high blood sugar levels (hyperglycemia) as a result of abnormal insulin production and/or insulin function." (PMID 38790901, 2024). "Damage to pancreatic islets or their improper function can lead to diseases such as diabetes, characterized by disturbances in glucose metabolism and insulin resistance." (PMID 38673817, 2024).